INS (insulin)
Diseases named in the same sentence as INS in open-access papers (continued):
Sharing a sentence is not in itself a finding about the gene and the disease.
Obesity (continued). "Thus, inactivation of FOXO signaling gives rise to an immunometabolism gene signature that is characteristic of obesity-induced insulin resistant states." (PMID 30502001, 2019). "Consequently, despite having a likely subtle defect in insulin secretion, Ppp1r15aΔC/ΔC mice were resistant to diet induced obesity, remaining leaner and less insulin resistant than their wild type littermates fed on a high-fat diet." (PMID 30814564, 2019). "Furthermore, we found that recurrent obesity or long-term consumption of the high-fat diet elevated serum glucose, insulin, and corticosterone levels, and that daisaikoto lowered serum cholesterol and free fatty acid levels." (PMID 31920693, 2019). "If blocking hypothalamic insulin signaling induces significant changes in food intake—which would chronically result in obesity or leanness—then glucose metabolism would be impaired or improved due to the resulting obesity and leanness, respectively." (PMID 30875909, 2019). "Here, we established that severe hyperglycemia during pregnancy could lead to obesity and increased risk of metabolism syndrome in female F2 offspring rats by affecting the expression of ARHGEF11 and insulin signaling molecules in the liver and muscles." (PMID 31612150, 2019). "Overnutrition, such as in HFD, induces obesity, together with a decrease of insulin sensitivity." (PMID 31083314, 2019). "This analysis highlighted an enrichment in many protein super-families modulated by RSV, of relevance in metabolic diseases and obesity, such as nuclear hormone receptor-type (e.g., PPARγ), insulin related, NF-κB, enolases, sirtuins, and nitric oxide related proteins." (PMID 30641865, 2019). "Exposure to ANAL (artificial light at night) could generate obesity, hyperlipidemia, and reduce the efficiency of insulin in promoting glucose uptake and utilization." (PMID 31195699, 2019). "Unlike butyrate which seems to play a protective role in the gut microbiome, acetate is thought to interact with the host parasympathetic nervous system to modulate insulin secretion and may promote obesity." (PMID 31098399, 2019). "Nefastin modulates appetite, Omentin improves insulin action and reduces obesity." (PMID 31357412, 2019). "The biological processes “Platelet degranulation,” “Positive regulation of glucose import” and “Cellular response to insulin stimulus,” already found modulated in obesity (PDGFB, SERPING1 ADIPOQ, PIK3R1, IGF1) were further enriched in ObCRC with respect to Ob individuals." (PMID 30838002, 2019). "The evidence suggests that the detrimental effect of high sugar intake on insulin responses could be more pronounced in subjects with overweight or obesity." (PMID 31888175, 2019). "In addition to cold exposure model, intermittent fasting also significantly stimulated the beiging of WAT and improved obesity and insulin sensitivity, and it also produced a shift in the gut microbial composition." (PMID 31316465, 2019). "Furthermore, the administration of either spermidine or spermine has been shown to be effective for improving glucose homeostasis and insulin sensitivity and reducing adiposity and hepatic fat accumulation in diet-induced obesity mouse models." (PMID 30923709, 2019). "Our findings suggest that the resistance of adipose tissue to the effects of insulin is, indeed, directly associated with the degree of obesity, independent of glucose tolerance." (PMID 30637483, 2019). "In obesity and/or T2D, a typical proinflammatory M1 polarization in the adipose tissue is observed which is associated with certain morbid factors such as increased levels of TNF-α, fatty acids, glucose, insulin, and obesity-induced hypoxia." (PMID 31718015, 2019). "In females, significant positive correlations were identified between serum L-carnitine level with obesity, serum total cholesterol, glucose, insulin, and IR in those with normal fasting glucose level (p < 0.05 for all), while none was found in those with hyperglycemia." (PMID 30972022, 2019).
Obesity (continued). "Impaired microvascular insulin signaling may develop before overt indices of microvascular endothelial dysfunction and represent an early pathological feature of adolescent obesity." (PMID 31352610, 2019). "In particular, obesity induces peripheral resistance to insulin-mediated glucose uptake." (PMID 31488172, 2019). "Among the treatment options for obesity, bariatric surgery is one of the most effective options, and studies have demonstrated the metabolic benefits such as increased insulin sensitivity, modulation of adipokine secretion and decreased local adipose and systemic inflammation." (PMID 30875990, 2019). "This suggests that the body likely defends fat mass over lean body mass, where insulin resistance could be instrumental in preserving fat mass (that normally leads to obesity)." (PMID 33499919, 2019). "Additionally, we determined little evidence of differential regulation of gene expression or protein content or activation of elements involved in adipose tissue insulin signaling in individuals with obesity in response to these interventions." (PMID 30925197, 2019). "Future studies may consider biomarkers of obesity related to glucose-insulin homeostasis, adipose tissue inflammatory biomarkers to further strengthen causal inference." (PMID 31826013, 2019). "Beyond the vasodilator and anti-atherogenic properties, eNOS-dependent NO, at physiological concentrations, positively impacts mitochondrial function and is required for mitochondrial biogenesis, brown AT signaling, and energy expenditure, displaying insulin sensitizing and anti-obesity effects." (PMID 31627295, 2019). "A diet rich in saturated fats causes inflammation in the hypothalamus, leading to resistance to insulin and leptin as well, consequently, the hypothalamus inflammation favor a prominent body weight, setting up a vicious cycle that eventually leads to obesity." (PMID 31683535, 2019). "Several studies have described correlations among insulin and obesity, metabolic parameters and dhCers linking them to the development of metabolic disorders, though the pathophysiological mechanisms associated with these molecules are still unknown." (PMID 31771303, 2019). "Obesity-dependent activation of JNK signaling was shown to impair insulin signaling." (PMID 30906281, 2019). "Transgenic (Tg) mouse models overexpressing PHB (PHB-Tg) and a phospho-mutant PHB (mPHB-Tg) from the fatty acid binding protein-4 (Fabp-4) gene promoter display sex-neutral obesity; however, obesity-related insulin resistance and metabolic dysregulation are male-specific." (PMID 31118075, 2019). "Therefore, in obesity the increased expression of PU.1 in adipocytes modifies the adipocyte PPARg cistrome resulting in impaired glucose tolerance and insulin sensitivity." (PMID 31611602, 2019). "These injections of insulin can result in hyperinsulinemia and influence ovarian steroidogenesis in the same way hyperinsulinemia as a result of obesity might." (PMID 31367382, 2019). "Hence, our findings offer suggestions for future investigation of this phenomenon and contribute to the understanding of the role of insulin and leptin resistance in obesity pathogenesis in humans." (PMID 30886629, 2019). "SREBP-1c activity persists even in insulin resistant states, as seen in obesity and T2D." (PMID 31137678, 2019). "Autophagy is regulated by the integrated action of insulin and mTOR, both altered in obesity." (PMID 31130916, 2019). "This pathology could occur in conditions of obesity accompanied with a decrease in cellular response of insulin-dependent tissues." (PMID 31412623, 2019). "Exercise had a more marked effect on the insulin/MAPK/mTORC1 signaling pathway than obesity per se." (PMID 31466137, 2019).
Obesity (continued). "These epigenetic modifications were observed in obesity, gestational diabetes, metabolic syndrome and concerned various molecular processes like glucose metabolism, insulin sensitivity, liver fibrosis, obesity-related carcinogenesis, adipogenesis or fetal/early postnatal programming." (PMID 31408957, 2019). "The absence of effects on other WAT depots indicated that scWAT was the target for maqui beneficial effects against diet-induced obesity and that at least part of the effects of berries on glucose metabolism and insulin sensitivity go through the improvement of adipose tissue functionality." (PMID 31480627, 2019). "Indeed, substantial evidence has mounted that some individuals with obesity remain nearly as insulin sensitive as lean counterparts while other individuals with a similar degree of obesity become insulin resistant." (PMID 31263701, 2019). "Obesity is a well-known risk factor for T2DM progression, and obesity-induced glucolipotoxicity (i.e., hyperglycemia and hyperlipidemia) inflicts oxidative stress, thus leading to impaired islet glucose-stimulated insulin secretion (GSIS) and apoptosis." (PMID 31121855, 2019). "Similarly, Zip13-deficient mice have enhanced beige adipocyte production and energy expenditure and this was concomitant with resistance to HFD-induced obesity, and improved glucose and insulin tolerance." (PMID 31266232, 2019). "These included changes in 5 immune function-related proteins, among which IL-6 and Ccl3 both decreased by exercise and correlated with obesity and insulin-sensitivity in our mice, likely due to increased and suppressed inflammation by HFD and exercise, respectively." (PMID 31019501, 2019). "Secondary complications of obesity have been suggested to be caused by the functional failure of white adipose tissue (WAT), leading to ectopic lipid deposition, lipotoxicity and systemic insulin resistance." (PMID 31418690, 2019). "Kinase-independent functions may act in concert or may be interconnected with the kinase activity, like PI3Kγ in diet-induced obesity and PI3Kβ in insulin signaling or they may act independently from each other, as shown by PI3Kγ in cardiac contractility." (PMID 31480354, 2019). "Licochalcone A could significantly attenuate serum leptin levels and promote serum adiponectin levels to reduce obesity and regulate insulin sensitivity in HFD-induced obese mice." (PMID 31083505, 2019). "In addition, obesity, through reducing insulin sensitivity and increasing the availability of glucose for maternal-fetal transport, promotes intrauterine growth." (PMID 31735163, 2019). "Interestingly, mice lacking IDO1 expression in macrophages and neutrophils exhibited normal weight gain and insulin sensitivity in obesity." (PMID 31921154, 2019). "The beneficial effect of solTNF neutralization in reducing intestinal inflammation in obesity is particularly important because intestinal immune alterations are a recognized contributor to metabolic syndrome comorbidities such as glucose and insulin impairment and CNS neurodegenerative processes." (PMID 31892368, 2019). "Experimental evidence suggested consumption of high-fructose products in rat models or in humans could lead to the development of metabolic syndrome, which is characterized by obesity, high blood pressure, and increased serum glucose, insulin and TG levels." (PMID 30814920, 2019). "Obesity may then result from a vicious cycle in which carbohydrate intake provokes insulin-induced fuel deposition in adipocytes with the increased adiposity then leading to insulin resistance and a further compensatory rise in insulin." (PMID 30809194, 2019). "Recent studies have shed light on the pivotal role of prolonged endoplasmic reticulum stress (ERS)-initiated activation of the unfolded protein response (UPR), the ensuing chronic low-grade inflammation, and altered insulin signaling in promoting obesity-compromised cardiovascular system (CVS)." (PMID 31551782, 2019).
Obesity (continued). "Furthermore, elevated fasting insulin levels observed in children with obesity were suggestive of impaired endogenous glucose regulation." (PMID 31623384, 2019). "Exercise training, in particular aerobic interval training, has been reported to reverse harmful remodeling of AT in high fat diet induced obesity in rats, by observed decreased systemic insulin resistance, decreased adipocyte size and increased capillary density in the AT." (PMID 31890043, 2019). "With obesity and raised insulin levels there is also a decrease in IGFBP-1 and IGFBP-2 levels and these reductions could potentially result in an increase IGF-availability in tissues." (PMID 30809194, 2019). "The SNP rs7799039 could impair LEP action diminishing the insulin resistance effect derived by a leptin resistant state during obesity." (PMID 30764545, 2019). "These authors concluded that elevated vaspin expression could represent a compensatory mechanism of insulin resistance, secondary to the metabolic complications of obesity." (PMID 30325336, 2019). "However, the expression of ARHGEF11 and insulin signaling molecules in muscle tissues showed an opposing trend, which suggests complex regulation patterns of obesity and metabolism in the offspring of gestational hyperglycemia parents." (PMID 31612150, 2019). "Insulin resistance syndrome including obesity, hyperglycemia, hyperlipidemia, and hypertension or insulin therapy in our donors might interfere with the insulin signaling pathway, leading to alteration of the INSR function." (PMID 31781030, 2019). "We found that recurrent obesity or long-term consumption of a high-fat diet elevated the serum levels of corticosterone, as previously observed, as well as the serum levels of glucose and insulin." (PMID 31920693, 2019). "In this study, we showed that the water extract of Caulis Spatholobi (WECS) has a significant effect in inhibiting body weight gain, decreasing adiposity, maintaining glucose homeostasis, reducing insulin resistance and improving hepatic steatosis in diet-introduced obesity (DIO) mice." (PMID 31627416, 2019). "The data for insulin were available from two studies of T2D and two studies of obesity." (PMID 30897796, 2019). "Dysregulation of leptin and insulin signaling pathways within this brain region may contribute not only to the development of obesity, but also systemically affect the peripheral organs, thereby manifesting as metabolic diseases." (PMID 31660128, 2019). "Altered metabolic states, for example in obesity, result in decreased insulin sensitivity in the skeletal muscle, liver, and adipose tissues that is counteracted by a compensatory increase in insulin secretion by β cells through an increase in both β cell function and mass." (PMID 31401713, 2019). "Furthermore, the impact of adipose tissue NRG4 on human obesity and insulin sensitivity was also evaluated." (PMID 30766490, 2019). "Obesity increases CSF insulin levels in rodents, sheep, and humans." (PMID 30875909, 2019). "Taken together, we identify that FMT may be associated with short-term statistically significant improvements in dysglycemia (insulin sensitivity) for patients with obesity and MS." (PMID 31557953, 2019). "Diagnosed animals are characterized by obesity and impaired cellular response to insulin." (PMID 31771123, 2019). "Adiponectin, a type of adipokine secreted exclusively from AT and abundant in plasma, is recognized as an insulin-sensitizing hormone, improving whole-body insulin sensitivity in models of genetic and diet-induced obesity via the activation of AMP protein kinase signaling." (PMID 31114678, 2019). "Circulating adiponectin levels are reduced in obesity, whereas the expressions of adiponectin receptors are increased, as evidenced by higher mRNA expressions of AdipoR1 in skeletal muscle in obese subjects and AdipoR2 in insulin-resistant subjects." (PMID 31718027, 2019).
Obesity (continued). "Although the effects of adiponectin as a potent insulin sensitizer and immune modulator are well-known, we show for the first time that adiponectin has the ability to modulate T cell functions in the context of obesity." (PMID 31736971, 2019). "The mechanisms through which obesity in mid-life may attenuate cognitive function involve possible changes in vascular function and increases in inflammation, insulin resistance, and oxidative stress." (PMID 31775713, 2019). "Thus, the administration of NR protects mice against obesity and glucose tolerance, increasing fatty acid oxidation and energy expenditure and improving insulin sensitivity." (PMID 31078136, 2019). "Insulin, insulin-like growth factor-1 (IGF1), leptin, adiponectin, steroid hormones, and cytokines are some host factors associated with obesity that not only influences the initiation and progression of breast cancer, but also affects its response to therapies." (PMID 31121868, 2019). "Previous studies found that MafB expression is induced in proliferative β cells during pregnancy and in obesity, suggesting MafB may play a unique role in β-cell adaptation under certain metabolic stresses that demand more insulin production." (PMID 31208980, 2019). "On the other hand, miR-130a improves insulin sensitivity in obesity." (PMID 31817583, 2019). "Moreover, in obese children it has been found that, in the early phase of obesity, alleles of the insulin gene variable number of tandem repeat (VNTR) locus are associated with different effects of body fatness on insulin secretion." (PMID 31035514, 2019). "Age, male, oral antidiabetic agents, insulin use, current smoking, current drinking, obesity, levels of triglycerides (TG), alanine aminotransferase (ALT), carbamide, eGFR, unconjugated bilirubin (IBiL), and β-blockers were significantly different across the GGT tertiles (all P < 0.05)." (PMID 30984786, 2019). "When exposed to high concentrations of insulin (10 μM), co-cultured adipocytes showed decreased intracellular TG content after 9 days, suggesting increased lipolysis, a physiological trend observed in obesity and in T2DM." (PMID 32133436, 2019). "Adipokines play a crucial role in regulating insulin sensitivity, adipogenesis, and obesity." (PMID 31137884, 2019). "During the last few decades, emerging research has focused on the role of the gut microbiota in metabolic diseases and has shown that gut microbiota dysbiosis is intertwined with various disorders, such as obesity, glucose intolerance, insulin sensitivity, and disturbances in serum lipid profiles." (PMID 31316465, 2019). "The ubiquitous complication of obesity is faulty insulin signaling in these tissues." (PMID 31013288, 2019). "In contrast to the three obesity-associated tumor types, melanoma, B cell lymphoma, and small cell lung cancer cell lines showed no mitochondrial oxidative response to insulin." (PMID 31188872, 2019). "The carbohydrate-insulin and energy balance hypotheses have distinctly different implications for understanding the etiology of obesity and devising effective strategies for preventing and treating it." (PMID 31815933, 2019). "We next investigated whether the beneficial effects of carvedilol on gluconeogenic enzymes, hepatic glucose production and muscular insulin signaling pathway were translated to the metabolic benefits of carvedilol treatment in HFD-induced obesity." (PMID 31682617, 2019). "Conversely, improving insulin resistance by exercise, and thereby hippocampal glucose metabolism might improve insulin signaling and neuroplasticity resulting in the alleviation of cognitive dysfunction in obesity." (PMID 31311133, 2019). "When we investigated whether the MRS might be tagging specific aspects of obesity-related physiology, we found it to be a strong marker of preserved insulin sensitivity." (PMID 31560688, 2019). "Obesity increases insulin secretion from pancreatic β-cells." (PMID 31208019, 2019).